CALM2 (calmodulin 2)
Diseases named in the same sentence as CALM2 in open-access papers (continued):
Sharing a sentence is not in itself a finding about the gene and the disease.
hepatocellular carcinoma (1 paper, 2021). A malignant tumor that arises from hepatocytes. "have denoted that CALM2 inhibition can hamper cell proliferation and colony formation in hepatocellular carcinoma (HCC) cells by inducing apoptosis." (PMID 34604066, 2021).
influenza (1 paper, 2013). An acute viral infection of the respiratory tract, occurring in isolated cases, in epidemics, or in pandemics; it is caused by serologically different strains of viruses (influenzaviruses) designated A, B, and C, has a 3-day incubation period, and usually lasts for 3 to 10 days. "The majority of the hits were novel; however, PANK4, NEK8, ITPKB, CALM2 and HK2 have been identified in other influenza screens." (PMID 23805279, 2013).
lung carcinoma (1 paper, 2023). "As previously demonstrated, CALM2 is linked to poor prognosis in lung cancer patients." (PMID 37470336, 2023). "miR‐651‐5p affects the proliferation, migration and invasion of lung cancer cells by regulating CALM2 expression." (PMID 37470336, 2023). "RT‐qPCR and western blot assay were conducted to test CALM2 expression in lung cancer tissues, and the experimental results indicated that CALM2 expression was elevated in lung cancer tissues compared with that in para‐cancerous tissues." (PMID 37470336, 2023). "miR‐651‐5p targeted and negatively regulated CALM2 expression, and CALM2 reversed the inhibiting effects of miR‐651‐5p on lung cancer cell malignant behaviors, including proliferation, migration, and invasion." (PMID 37470336, 2023). "The expression levels of miR‐651‐5p and CALM2 in lung cancer tissues and cells were tested, and the connection between miR‐651‐5p expression and clinicopathological characteristics of lung cancer patients was further analyzed." (PMID 37470336, 2023). "This study expounds that miR‐651‐5p affects the proliferation, migration, and invasion of lung cancer cells by regulating CALM2 expression." (PMID 37470336, 2023). "At the outset, we have explored miR‐651‐5p and CALM2 expression in lung cancer tissues and cells and the connection between clinicopathological characteristics and poorer prognosis of patients with lung cancer with miR‐651‐5p expression." (PMID 37470336, 2023). "Given the complexity of the interplay among miR‐651‐5p and CALM2, and the knowledge vacancy, there is a pressing requirement to translate the mechanism of these two factors in lung cancer." (PMID 37470336, 2023). "To further investigate whether miR‐651‐5p affects lung cancer cell functions through CALM2, we set up the miR‐651‐5p mimic + oe‐NC group and the miR‐651‐5p mimic + oe‐CALM2 group for H1299 cells." (PMID 37470336, 2023). "In summary, the research demonstrates that miR‐651‐5p impacts lung cancer cell proliferative, migratory, and invasive behaviors by regulating CALM2 expression, which may renew the existed knowledge of miR‐651‐5p/CALM2 axis‐targeted mechanism in lung cancer." (PMID 37470336, 2023). "Thus, this study is to disinter the mechanism of miR‐651‐5p/CALM2 axis in lung cancer with the findings exhibiting that miR‐651‐5p affects lung cancer cell proliferative, migratory, and invasive behaviors through the regulation of CALM2 expression." (PMID 37470336, 2023). "Therefore, this research intends to explore the molecular mechanism of the miR‐651‐5p/CALM2 axis in the malignant behaviors of lung cancer cells." (PMID 37470336, 2023). "It is reported that CALM2 is involved in poor prognosis in lung cancer patients." (PMID 37470336, 2023). "Therefore, overexpression of CALM2 partially reversed the apoptosis‐promoting effect of miR‐651‐5p mimic on lung cancer cells, which confirmed that the inhibitory effect of miR‐651‐5p on lung cancer was achieved through negative regulation of CALM2 expression." (PMID 37470336, 2023). "This research intends to explore the molecular mechanism of the microRNA‐651‐5p (miR‐651‐5p)/Calmodulin 2 (CALM2) axis in the proliferation, migration, and invasion of lung cancer cells." (PMID 37470336, 2023). "In general, the independent function of miR‐651‐5p and CALM2, together with their multilateral interplay in lung cancer, has not been extensively explored." (PMID 37470336, 2023).
non-compaction cardiomyopathy (1 paper, 2022). Left ventricular non-compaction (LVNC) is characterized by prominent left ventricular trabeculae and deep inter-trabecular recesses. "We herein report what appears to be the first case of fetal non-compaction cardiomyopathy in both ventricles accompanied by a mutation in the calmodulin gene (CALM2)." (PMID 36507129, 2022).
osteosarcoma (1 paper, 2018). A usually aggressive malignant bone-forming mesenchymal neoplasm, predominantly affecting adolescents and young adults. "Moreover, many MYC bound super enhancer genesincluding CDK6, TGFB and CALM2 are downregulated upon THZ1 treatment, further confirming that role of THZ1 in targeting super enhancer signaling in osteosarcoma." (PMID 29644114, 2018).
cancer (12 papers, 2010 to 2025). A tumor composed of atypical neoplastic, often pleomorphic cells that invade other tissues. "The role of CALM2 in cancer is less well understood but may be linked to cancer since it is involved in controlling calcium signaling." (PMID 20370918, 2010). "Using the Cancer Cell Line Encyclopedia (CCLE), we assessed the correlation between the expression of the three genes encoding human CaM (CALM1, CALM2 and CALM3) and the IC50 values for CWHM-974 and FLU in the cancer cell lines tested." (PMID 37909019, 2023). "Western Blot measured CALM2 expression in 12 GC tissues, indicating that by contrast to para-carcinoma tissues, CALM2 was highly expressed in GC tissues." (PMID 34604066, 2021). "To understand the biological function of CALM2, we first examined CALM2 expression in GC tissues and para-carcinoma tissues of 31 IHC cases." (PMID 34604066, 2021). "We chose two cancer-associated genes, CD9 and CALMODULIN 2 (CALM2), highly expressed in both cell lines, and functionally validated the role of HuR in regulating their expression." (PMID 20370918, 2010). "The findings demonstrated the cancer-promoting function of CALM2 in GC." (PMID 34604066, 2021). "All the findings denoted that CALM2 exerted a cancer-promoting function in GC." (PMID 34604066, 2021). "This preliminary data could hint on how an increased expression of BC200 in nulliparous women or cancer cells may be Cis regulating the expression of CALM2." (PMID 31646972, 2019). "Similarly, CALM2 and CALM3 also had high prognostic and diagnostic potentials in human cancers." (PMID 35096010, 2021). "CALM1/CALM2/CALM3, the latent IPF-features are the known downstream targets of KNG1 (ligand)—BDKRB1 (receptor) signaling (KEGG: hsa05200, Pathways in cancer)." (PMID 38081956, 2023). "Slight discrepancies were observed for CALM2 in G1 cancer and for HRH4 in G3 cancer." (PMID 34768392, 2021). "A decrease in expression regardless of cancer grade was observed for CALM2, DRD5, ICAM1, while EGR1, HRH1, HRH2, HRH3 were overexpressed." (PMID 34768392, 2021).
tumor (9 papers, 2021 to 2025). "Ganggang Mu and colleagues investigated the tumor-associated macrophage (TAM) environment and reported that calmodulin 2 (CALM2) plays a key role." (PMID 39309860, 2024). "It was revealed that in GC tumor tissues and GC cells, in contrast with the Vector group, CALM2 overexpression greatly facilitated JAK2 and STAT3 phosphorylation and elevated the protein expressions of HIF-1 and VEGFA." (PMID 34604066, 2021). "Here, CALM2 was discovered to display a high expression in GC tissues and cells, which correlated with poor prognosis and malignant tumor progression." (PMID 34604066, 2021). "In in-vivo experiments, CALM2 boosted tumor growth and lung metastasis." (PMID 34604066, 2021). "It came to light that CALM2 played a carcinogenic role in tumor growth and metastasis in vivo." (PMID 34604066, 2021). "In in-vivo trials, it was also disclosed that highly-expressed CALM2 could facilitate tumor growth." (PMID 34604066, 2021). "Further analysis of DEGs in the pseudotime trajectory showed early high expression of CALM1 and CALM2 in the subcluster 1, and late up-regulation of RET in the subcluster 2, suggesting the persistent dysregulation of kinase signals over tumor evolution." (PMID 38407266, 2024). "Calmodulin which is encoded by CALM1, CALM2, and CALM3 genes, plays a significant role in non-tumor cell migration as well as tumor migration and metastasis." (PMID 36506940, 2022).
cardiac diseases (1 paper, 2025). "Among 244 genes associated with cardiac diseases, three candidate variants with high confidence of pathogenicity were identified in the UTRs of SCO2, CALM2 and TBX3 based on a rigorous filtering strategy." (PMID 39266800, 2025).
cardiovascular diseases (1 paper, 2024). "Similarly, many genes, including CALM2, PDCD4, TXNIP, CYP11B2, P2Y12, and ROCK1, have been identified as downstream targets of GAS5 in cardiovascular diseases." (PMID 38812041, 2024).
myopathy (1 paper, 2021). A disease of the muscle in which the muscle fibers do not function properly. "Furthermore, its calcium ion dependency could indicate some relationship between the downregulation of CALM2 and DNASE1L3, narrowing the hypothesis that the dysregulation of calcium signaling is one of the most important pathways contributing to WS myopathy." (PMID 34381378, 2021).
renal disease (1 paper, 2014). "The calmodulin 2 (CALM2) gene encodes a member of the human calmodulin family, and polymorphisms in this gene have been associated with dialysis survival in T2D-associated renal disease." (PMID 25009623, 2014).
CALM2 also shares sentences with these, for which no sentence is quoted: Arrhythmia (4 papers); colon cancer (2); idiopathic ventricular fibrillation (2); acute myocardial infarction (1); alcoholism (1); amyloidosis (1); Bradycardia (1); Brugada syndrome type 1 (1); Cognitive impairment (1); colorectal adenoma (1); cystic fibrosis (1); diabetic nephropathy (1); embryonic carcinoma (1); Huntington disease (1); left ventricular hypertrophy (1); lymphoma (1); metastasis (1); neuroblastoma (1); neurodegenerative disease (1); schizophrenia (1); stomach adenocarcinoma (1); thyroid cancer (1); type 2 diabetes (1); ventricular tachycardia (1).